RB1 (RB transcriptional corepressor 1)
Diseases named in the same sentence as RB1 in open-access papers (continued):
Sharing a sentence is not in itself a finding about the gene and the disease.
tumor (continued). "In tumor-bearing conditions, Rb1 epigenetic silencing favors PMN-MDSC development and its deletion promotes accumulation of monocytic precursors that can give rise to PMN-MDSCs." (PMID 38421883, 2024). "Other studies in ovarian, bladder, and localized prostate cancer have pointed to similar conclusions in that tumors with RB1 deletions were found to harbor a distinct immune profile due to the presence of tumor-infiltrating lymphocytes." (PMID 38396008, 2024). "We provide evidence of a nonsense germline pathogenic variant in the RB1 gene and the presence of the EWRS1/ERG fusion gene in EWS tumor tissue in our patient." (PMID 39596402, 2024). "Oncolytic viral vectors utilize the dysfunctional RB1 pathway with increased expression of E2F to target tumour cells." (PMID 37705787, 2023). "As a tumor suppressor gene, RB1 is a negative regulator in the progression of the cell cycle via the regulation of the E2F transcription factors." (PMID 36761763, 2023). "This difference seems unrelated to primary tumor grade (five/six grade 2/3 tumors developed a CDKN2A/RB1 alteration upon progression to grade 4 vs. six/six grade 2/3 tumors without progression-related alteration, respectively, p = 1.0, Fisher’s exact test)." (PMID 37932833, 2023). "Cell-cycle-associated genes RB1 and cyclin-dependent and aurora kinases were most expressed in BCM-15057, HCI-011, and HCI-013, corresponding to the tumor growth rate, as well as to the proportion of cells in the G2M/S phase in each model." (PMID 37370789, 2023). "They suggested that this happened due to microRNA-335 ability to decrease the expression of the tumor-suppressing human retinoblastoma 1 (Rb1) protein." (PMID 36883085, 2023). "FOXM1 controls RB1 in two opposing ways, either to turn off the canonical cell cycle inhibitory function of RB1 to enhance cell proliferation or to engage RB1 within repressive transcriptional complexes, which ultimately promote tumor metastasis." (PMID 37686402, 2023). "Of the 122 patients with germline BRCA2 mutations, tumor mutational analysis showed the somatic enrichment of MYC and RB1." (PMID 36980743, 2023). "The interplay between tumor suppressor proteins IFN-β and RB1 is central in this new mechanism of surveillance for selective suppression of tumor and transformed cells, while engaging their normal cell counterparts in regular cell cycle and differentiation." (PMID 37182173, 2023).
tumor (continued). "For instance, miR-106a was been found to target retinoblastoma protein (RB1), a critical tumor suppressor involved in cell cycle regulation." (PMID 37627777, 2023). "The tumor was tested for RB1 gene aneuploidy by FISH and underwent molecular genetic testing by TrueSight Illumina Oncology 500 NGS panel." (PMID 37401932, 2023). "This study is the first to examine the SCNA status of both AH and tumor samples while simultaneously analyzing RB1, BCOR, CREBBP, and MYCN for SNV disease drivers." (PMID 37239954, 2023). "Among 31 single HMTs with expression in all samples, 19 showed a marked up-regulation in RB1-mutant tumours, with particularly notable up-regulation of EZH2, DOT1L, and NSD2, while only 5 displayed a clear down-regulation." (PMID 37883365, 2023). "NNMT expression was significantly reduced in RB1-mutant tumours, consistent with its anticorrelation to HMTs." (PMID 37883365, 2023). "When phosphorylated by cyclin D, cyclin-dependent kinase 4 (CDK4), and CDK6, RB1 will be inactive, resulting in an unregulated progression through the cell cycle and tumor growth." (PMID 36674870, 2023). "In detail, retinoblastoma 1 (RB1) is a tumor suppressor involved in cell cycle regulation, cell differentiation, proliferation, and death." (PMID 36673351, 2023). "Other tumor suppressors, including E-cadherin 31 and the retinoblastoma protein (RB1) 32 are MDM2 substrates for degradation." (PMID 37496993, 2023). "The first gene in the top 10 most informative genes based on the CNV information is the first ever known tumor suppressor “RB1”." (PMID 36717667, 2023). "This included ST3932 tumours which in addition to being PTEN null, PIK3CA mutant also carried a RB1 mutation." (PMID 37543694, 2023).
tumor (continued). "Overall, these data demonstrate that the interaction between systemic alterations (i.e. diet, sex) and the tumor is dependent on the genotype of the tumor itself (Pten versus Rb1 deletion)." (PMID 36472402, 2023). "Similar results were obtained in all three SCLC cell lines examined, suggesting a broad role of the RB1-YAP axis in modulating tumor metastasis and YAP transcription in SCLC." (PMID 37739954, 2023). "Similar to other polyomaviruses, MCPyV LT contains an LXCXE motif essential for binding and inhibiting the RB1 tumor suppressor to overcome the G1/S cell-cycle checkpoint." (PMID 36719743, 2023). "In the first situation, recall that cyclin D-CDK4/6 and cyclin E-CDK2 kinase complexes phosphorylate and inactivate the RB1 tumor suppressor during the G1-to-S transition, thereby preventing its association with E2F transcription factors." (PMID 37686402, 2023). "In these hematopoietic cancer cells, IFN-β exerts its tumor suppressor function via RB1-mediated G1/G0 growth arrest." (PMID 37182173, 2023). "We biopsied tumor specimens from five patients with PR and PD to detect the protein and mRNA levels of RB1, CDKN2B, PCNA, and MCM7." (PMID 37781033, 2023). "We detected a single breakend SV joining a centromere sequence of chromosome 13 and complex rearranged regions in RB1, a well-characterized tumor suppressor gene located in the region distant from the centromere sequences." (PMID 37336583, 2023). "Targeted sequencing has been applied to both AH and tumor samples to profile gene regions of interest (primarily the RB1 gene) for SNV variants, along with small insertions and deletions that negate RB1 protein function." (PMID 37239954, 2023). "For instance, retinoblastoma tumor suppressor (RB1) was identified as one of the suppressor genes that hypermethylated in tumor tissues." (PMID 37893440, 2023). "Several studies showed that epigenetic deregulation of tumor-promoting pathways is important for RB formation and progression beyond RB1 inactivation." (PMID 37658463, 2023). "It has been reported that the downregulation of CDK6 also suppresses its interacting gene, RB1—a tumor suppressor gene." (PMID 37900178, 2023). "Western blot analysis validated tumour suppressor loss in Pten single knockout (SKO) and Pten;Rb1 double knockout (DKO) basal-derived organoids." (PMID 38049604, 2023). "An increased average value of PD-L1 in the tumor inflammatory infiltrate was associated with a high FIGO score (p = 0.002) in malignant tumors, as well as an increased percentage of Rb1-positive nuclei (p = 0.047) in all entities." (PMID 37373854, 2023). "Targeting cyclin-dependent kinase 4 and 6 (CDK4/6), the proteins controlling cell cycle entry, has become an attractive tumor treatment strategy for RB Transcriptional Corepressor 1 (RB1) wild-type patients." (PMID 37452037, 2023). "In all cancer types RB1-mutant tumours had higher mean total HMT expression; in a pan-cancer analysis, we observed that this difference was highly significant." (PMID 37883365, 2023). "More than 10 years after Knudson’s discovery, RB1 gene was the first tumor suppressor gene to be identified and cloned." (PMID 37658463, 2023).
tumor (continued). "Our results show that the frequency of inactivating CDKN2A/RB1 alterations is highest after tumor progression following post-operative combination therapy, and PDGFRA/MET alterations co-appear with CDKN2A inactivation." (PMID 37932833, 2023). "With similar intent, SCNA profiling via low-pass whole genome sequencing (WGS) has been utilized to investigate RB1 loss on chromosome 13, along with additional RB-SCNA signatures (i.e., chr6p gains), in both AH and tumor samples." (PMID 37239954, 2023). "The most known and best studied CTDSP1/2/L target is the retinoblastoma protein (Rb1), a potent tumor suppressor." (PMID 37629167, 2023). "Newer data indicate that both p107 and p130 are involved in the senescence entry of tumor cells that have lost RB1 function." (PMID 37182173, 2023). "We confirmed that the novel aberrant transcript isoforms result from focal genomic deletions that deleted multiple exons (in NOTCH1) or one exon (in RB1) from the tumor genome." (PMID 37553321, 2023). "RB1 is a tumor suppressor whose homozygous inactivation catalyzes development of the rare tumor retinoblastoma." (PMID 36124964, 2023). "This makes inactivation of the CDKN2A/RB1 pathway a major mechanism for grade 4 tumor development, at least with the treatment schemes used." (PMID 37932833, 2023). "This ‘pro-metastatic’ role of RB1 when bound to FOXM1 flies against the conventional view of RB1 as a tumor suppressor." (PMID 37686402, 2023). "Previous studies have reported RB1 as the first TF identified to suppress tumors by negatively regulating the cell cycle, and inhibition of RB1 promotes tumor invasion and metastasis in NSCLC." (PMID 38057344, 2023). "Inhibitors of RB1-deficiency or MET plus RHO-signaling cooperate to block cell migration and drive tumor cell-death." (PMID 37463901, 2023). "Among the genomic biomarkers able to discriminate transformed tumours (hEMT, MES) from the epithelial state, we identified genes that have been previously linked with cell migration, invasion and EMT, such as RB1, VHL, ERBB2, ARHGAP26, PRDM1, APC." (PMID 36774358, 2023). "In vivo, rucaparib treatment significantly reduced tumor volume in RB1-knockout (RB1-KO) xenograft mice." (PMID 37937640, 2023). "We were also able to confirm all germline RB1 CNAs that were detected by the clinical blood test for both the AH and tumor in our assay." (PMID 37239954, 2023). "The RB1 gene represents another bona-fide tumor suppressor gene that has long been known to become inactivated through DNA methylation in cancer." (PMID 36084090, 2022).
tumor (continued). "In this study, we found that the protein level of RB1 was higher in OC tissues than that in adjacent non-tumor ovarian samples." (PMID 35299734, 2022). "The protein expression level of RB1 was upregulated in tumor tissues than that in adjacent normal tissues and was mainly localized in the nucleus (P = 0.019)." (PMID 35299734, 2022). "Retinoblastoma (RB) protein, encoded by RB1 gene acts as a tumor suppressor by interacting with others proteins such as E2F family proteins to inhibit cancer-promoting activities such as accelerated cell cycle progression." (PMID 36274096, 2022). "The immunohistochemistry (IHC) was performed to compare the expression level of RB1 in normal tissues and tumor samples, and to predict the prognosis of OC." (PMID 35299734, 2022). "In contrast, Rb1 restoration blocks lung tumor progression to more advanced grades, impairs metastatic progression, and transiently inhibits tumor growth." (PMID 35228570, 2022). "Some well known oncogenes, such as AKT3, and tumor suppressors, such as RB1 and PARK2 emerged in the high or low CNV regions." (PMID 35244719, 2022). "The RB1 is a tumor-suppressing gene regulating survival, proliferation, angiogenesis, migration, differentiation, apoptosis, senescence and drug-resistance." (PMID 35054871, 2022). "To verify that miR‐192‐5p/RB1 promotes the Treg cell differentiation by IL‐10 secretion, we co‐cultured PBMCs with tumour cells under different conditions." (PMID 35969010, 2022). "A previously reported model indicated that RB1 functions as an essential tumour suppressor, which physically interacts with RBAK." (PMID 35735060, 2022). "Abemaciclib most efficiently crosses the blood brain barrier, and effectiveness of these drugs is best predicted by intact RB1 expression in the tumor cells." (PMID 35911672, 2022). "Exome sequencing of the NEC913 PDX tumor revealed an RB1 frameshift insertion (1091_1092insCG) leading to a premature stop codon." (PMID 35454817, 2022). "Specifically, RB1 can downregulate the transcriptional target of nuclear factor-kappa B (NF-κB) via interacting with NF-κB to promote tumor immunity." (PMID 35299734, 2022). "As a tumor suppressor gene, RB1 has a key role in regulating cell cycle progression and cell differentiation." (PMID 36714839, 2022).